FAM86C1P (family with sequence similarity 86 member C1, pseudogene)
Synonyms: FAM86C; FAM86C1; FLJ10661; FLJ27199
Gene: Transcribed unprocessed pseudogene on chromosome 11 (71,787,537 to 71,799,660, forward strand). Ensembl gene ENSG00000158483.
Diseases named in the same sentence as FAM86C1P in open-access papers:
FAM86C1P is named in the same sentence as 7 diseases in open-access papers, as found by Europe PMC text mining. Sharing a sentence is not in itself a finding about the gene and the disease. The quoted sentences say what the papers report.
tumor (2 papers, 2017 to 2024). "In particular, among the genes shared in the three samples, KCNJ12 and FAM86C1P genes show significantly lower VAF in the primary tumor compared to metastases." (PMID 39409151, 2024).
FAM86C1P also shares sentences with these, for which no sentence is quoted: breast carcinoma (1 paper); gingivitis (1); Insulin resistance (1); liver cancer (1); Obesity (1); osteoporosis (1).